IMPACT (impact RWD domain protein)
Description:
Translational regulator that ensures constant high levels of translation upon a variety of stress conditions, such as amino acid starvation, UV-C irradiation, proteasome inhibitor treatment and glucose deprivation. Plays a role as a negative regulator of the EIF2AK4/GCN2 kinase activity; impairs GCN1-mediated EIF2AK4/GCN2 activation, and hence EIF2AK4/GCN2-mediated eIF-2-alpha phosphorylation and subsequent down-regulation of protein synthesis. May be required to regulate translation in specific neuronal cells under amino acid starvation conditions by preventing GCN2 activation and therefore ATF4 synthesis. Through its inhibitory action on EIF2AK4/GCN2, plays a role in differentiation of neuronal cells by stimulating neurite outgrowth.
Synonyms: RWDD5
Tractability: PROTAC: ubiquitination databases record sites on it; its protein half-life has been measured.
Gene: Protein-coding gene on chromosome 18 (24,426,634 to 24,453,531, forward strand). Ensembl gene ENSG00000154059.
Subcellular location: Cytoplasm
Subcellular location (Human Protein Atlas): Nucleoplasm
Pathways (Reactome):
Cellular responses to stimuli: Response of EIF2AK4 (GCN2) to amino acid deficiency
Gene Ontology:
Molecular function: protein binding; protein sequestering activity; actin binding; ribosome binding
Biological process: cellular response to amino acid starvation; GCN2-mediated signaling; intracellular signal transduction; negative regulation of transcription by RNA polymerase II; neuron projection extension; positive regulation of neuron differentiation; regulation of cytoplasmic translational initiation in response to stress; regulation of translational initiation
Cellular component: cytoplasm
Genetic constraint (gnomAD): Loss-of-function variants: 12 observed, 13.54 expected, observed/expected ratio (o/e) 0.89, 90% interval 0.57 to 1.43. The upper end of that interval is the gene's LOEUF score, 1.43, which puts it in group 5 of 6, group 1 being the genes least tolerant of losing a copy. Missense variants: 150 observed, 140.8 expected, observed/expected ratio (o/e) 1.07, 90% interval 0.93 to 1.22. Synonymous variants: 46 observed, 47.54 expected, observed/expected ratio (o/e) 0.97, 90% interval 0.76 to 1.24.
Homologues: Orthologues: macaque IMPACT (99% identical), chimpanzee IMPACT (99% identical), dog IMPACT (92% identical), pig IMPACT (92% identical), rabbit IMPACT (89% identical), guinea pig IMPACT (83% identical), mouse Impact (81% identical), rat Impact (80% identical), zebrafish impact (59% identical), tropical clawed frog impact (53% identical), Caenorhabditis elegans impt-1 (32% identical).
Diseases named in the same sentence as IMPACT in open-access papers:
IMPACT is named in the same sentence as 11 diseases in open-access papers, as found by Europe PMC text mining. Sharing a sentence is not in itself a finding about the gene and the disease. The quoted sentences say what the papers report.
Acute myeloid leukaemia (1 paper, 2018). "Acute myeloid leukaemia, pulmonary squamous cell carcinoma, prostatic adenocarcinoma and renal chromophobe tumours showed the highest expression of IMPACT relative to matching normal tissues (2.1-fold to 2.8-fold greater, respectively)." (PMID 30466445, 2018). "Intriguingly, 2.6-fold greater IMPACT expression was observed in Diffuse large B-cell lymphoma compared to Acute myeloid leukaemia; two haematological malignancies in TCGA." (PMID 30466445, 2018). "Moreover, IMPACT expression inversely correlated to a higher degree with IMPACT promoter methylation in Diffuse large B-cell lymphoma (ρ = − 0.85) compared to Acute myeloid leukaemia (ρ = − 0.35)." (PMID 30466445, 2018).
glioma (1 paper, 2018). A benign or malignant brain and spinal cord tumor that arises from glial cells (astrocytes, oligodendrocytes, ependymal cells). "GL261 glioma lines engineered to overexpress IMPACT were shown to remain viable to a greater extent than wild type GL261 cells when cultured under limiting tryptophan concentrations." (PMID 30466445, 2018). "We used the murine GL261 glioma line in our initial experimental studies to obtain evidence that IMPACT may be involved in enabling cancer cells to better survive periods of low tryptophan availability." (PMID 30466445, 2018).
nutritional deficiency (1 paper, 2025). "At the A + U extreme, IMPACT and ANKRD26 are two genes that mediate cellular adjustments to nutritional deficiency." (PMID 40341320, 2025).
Obesity (1 paper, 2019). Accumulation of substantial excess body fat. "We then asked whether the lack of IMPACT would protect mice from obesity induced by a high-fat diet (HFD)." (PMID 31166980, 2019).
prostate adenocarcinoma (1 paper, 2018). "However, a striking association between tryptophan metabolism, IMPACT, regulation of eIF2 and the cellular response to amino acid starvation was noted in prostate adenocarcinoma." (PMID 30466445, 2018). "A similar pattern emerges in prostate adenocarcinoma, although the clustering of IMPACT with the mTOR pathway is more distant compared to that in thyroid carcinoma." (PMID 30466445, 2018). "Prostate adenocarcinoma was selected because it shows the strongest correlations between the expression of IMPACT and the other genes examined." (PMID 30466445, 2018).
thyroid carcinoma (1 paper, 2018). "In thyroid carcinoma, the regulation of translation initiation factor eIF2, mTOR pathway and IMPACT were found to be functionally related to each other." (PMID 30466445, 2018).
cancer (3 papers, 2018 to 2022). A tumor composed of atypical neoplastic, often pleomorphic cells that invade other tissues. "In a subset of cancer types examined, high IMPACT expression was associated with low activity of stress response pathways and decreased expression of key stress response mRNAs." (PMID 30466445, 2018). "In a subset of clinical cancers, high IMPACT expression associated with decreased activity of pathways and genes involved in stress response and with increased activity of translational regulation such as the mTOR pathway." (PMID 30466445, 2018). "Taken in sum, the association of IMPACT copy number gain with gene expression for the majority of TCGA cancer types, suggests that IMPACT gene amplification may be a main driver of IMPACT expression in human cancers." (PMID 30466445, 2018). "A broad range of cancer types were found to express IMPACT at higher levels than that of corresponding normal tissues, and in many cases, the high expression appears to be driven by IMPACT amplification." (PMID 30466445, 2018). "These experimental results are consistent with higher IMPACT expression conferring a greater survival advantage to cancer cells during periods of tryptophan deprivation." (PMID 30466445, 2018). "Taken together, the data from the bioinformatics and the experimental studies reported here, suggest that high IMPACT expression benefits cancer cell survival during periods of accelerated tryptophan catabolism induced by IDO1." (PMID 30466445, 2018). "On the other hand, in twenty-one (81%) cancer types, IMPACT expression positively correlated (ρ = 0.25 to 0.69; P < 0.05) with IMPACT copy number gain, consistent with IMPACT amplification in the majority of TCGA tumour samples." (PMID 30466445, 2018). "Taken together, these correlations are compatible with IMPACT ameliorating a stress response induced by the accelerated tryptophan catabolism in a subset of cancer types." (PMID 30466445, 2018). "In summary, we found concordant correlation signatures of IMPACT expression with genes and pathways involved in regulation of stress response and translation in a subset of cancers." (PMID 30466445, 2018). "The majority of the cancers examined expressed significantly (two-tailed permutation test, P ≤ 0.05) higher levels of IMPACT compared to their normal tissue counterparts." (PMID 30466445, 2018). "The bioinformatics data together with our laboratory studies, support the hypothesis that IMPACT mediates a protective mechanism allowing cancer cells to overcome microenvironmental stresses such as tryptophan deficiency." (PMID 30466445, 2018). "The role of IMPACT in cancer is very much understudied, but in normal mammalian cells, IMPACT has been shown to have a similar role as the YIH1 protein in yeast; inhibiting activation of the general control non-derepressible 2 (GCN2) kinase that senses amino acid scarcity." (PMID 30466445, 2018). "As a first step towards understanding the role of IMPACT in cancer, we carried out a bioinformatic meta-analysis of IMPACT mRNA expression in 28 cancer types from the TCGA compared to that in 24 corresponding normal tissues from the GTEx data set belonging to 20 organ classifications." (PMID 30466445, 2018). "Overall, most cancer types examined have hypo-methylated IMPACT promoter (median β < 0.13) and their IMPACT expression do not substantially anti-correlate (ρ > − 0.36) with IMPACT promoter methylation." (PMID 30466445, 2018). "The lncRNA GPRC5D-AS1 with CNVs driving the dysregulation of downstream cancer genes such as PRKCI, SEM1, TBL1XR1, IMPACT, and RPL22L1 further disturbed the activities of NOTCH signaling pathway that is usually inactivated in LUSC." (PMID 34925461, 2021). "We found IMPACT to be upregulated and frequently amplified in a broad range of clinical cancers relative to their non-malignant tissue counterparts." (PMID 30466445, 2018).
tumour (1 paper, 2018). "The meta-analyses results indicate that in a subset of tumour types, high IMPACT expression associates with decreased expression of stress response pathways and the key ISR effector genes ATF4 and DDIT3 (CHOP)." (PMID 30466445, 2018). "We next investigated whether IMPACT expression levels are associated with mRNA expression signatures of stress response to tryptophan deprivation in tumours." (PMID 30466445, 2018). "Increased IMPACT expression in tumours compared to matching normal tissues indicates IMPACT’s important role in neoplasia." (PMID 30466445, 2018). "The association of IMPACT expression with genes and pathways involved in regulation of stress response in our bioinformatics analysis, while modest, is never-the-less compatible with IMPACT having a biological role as an inhibitor of the ISR in human tumours." (PMID 30466445, 2018).
IMPACT also shares sentences with these, for which no sentence is quoted: breast invasive carcinoma (1 paper); diffuse large B-cell lymphoma (1); kidney clear cell carcinomas (1).